TNF (tumor necrosis factor)
Diseases named in the same sentence as TNF in open-access papers (continued):
Sharing a sentence is not in itself a finding about the gene and the disease.
liver fibrosis (continued). "HCV patients with mild liver fibrosis (F1-2) showed stronger connections between proinflammatory cytokines with a clear positive connection of IL-10 controlling the TNF node." (PMID 26742960, 2016). "During schistosoma infection, TNF-α participated not only the cell-mediated protective immunity, but also involved in the immune responses that affect liver fibrosis and hepatosplenomegaly." (PMID 26891172, 2016). "Other transcription factors like nuclear factor-like 2 (Nrf2) and cytokines (TNF-α, IL-6, IL-13) can also activate HSCs and promote liver fibrosis." (PMID 25897319, 2015). "Treatment with genistein decreased levels of inflammation mediators, including IL-6, TNF-α, and myeloperoxidase, through downregulation of NF-κB in alcohol- and CCl4-induced liver fibrosis in rats." (PMID 25897319, 2015). "On the contrary, IL-10 gene therapy reduced the expression of profibrotic genes, including TGF-β and TNF-α, and reversed the thioacetamide-induced hepatic fibrosis in mice." (PMID 26199463, 2015). "In conclusion, MMP2, MMP9 and TNF-α showed high reproducibility to differentiate patients with liver fibrosis (F1–F4) from control group." (PMID 26464613, 2015). "Consistent with the results, we observed that the liver fibrosis was significantly reduced and the inflammation response was obviously alleviated by the down-regulation of pro-inflammatory cytokines IL-6 and TNF-α after the treatment with PZQ." (PMID 25582427, 2015). "MMP2, MMP9 and TNF-α showed a significant elevation in patients with liver fibrosis (F1–F4) compared to control group (p=0.001)." (PMID 26464613, 2015). "Mediating anti-fibrosis effects in hepatic fibrosis rats through down-regulating the TNF-alpha and NF-kB expression." (PMID 26633388, 2015). "Higher hepatic TNF-α levels and more severe liver fibrosis can be observed in the carbon tetrachloride (CCl4) treated IL-10 KO mice than in the wild type animals." (PMID 26199463, 2015). "Kupffer cells and T lymphocytes and the fibrotic and inflammatory cytokines, such as TGF-β, TNFα, IL-6, and IL-17, produced by them are also involved in the progression of hepatic fibrosis and activation of hepatic stellate cells." (PMID 26358689, 2015). "In this study, we found that the expression levels of hepatic TSPO, TGF-β1, PDGF-β, and TNF-α mRNAs were increased progressively by 6 weeks of CCl4 treatment, at which time liver fibrosis had almost developed into cirrhosis." (PMID 26612465, 2015). "The present study was designated to correlate the levels of MMP-2, MMP-9 and TNF-α with the pathogenesis of chronic liver diseases (CLD) caused by HCV, it also aimed at using them as possible non-invasive serum markers for liver fibrosis." (PMID 26464613, 2015). "In this study, we found that BBG significantly ameliorated liver fibrosis and down-regulated fibrosis-related pro-inflammatory cytokines IL-6, TNF-α, IL-1β, and PDGF." (PMID 25933224, 2015). "With respect to this study, G-Rg1 has been shown to inhibit the production of TNF-α and has been shown to significantly attenuate the development of liver fibrosis." (PMID 25431611, 2014). "In this work we observed a strong anti-inflammatory effect of Omegaven® on human monocytes activated by LPS, nearly suppressing IL-6, IL-8, IL-1β and TNFα whose elevated levels have been associated previously with NASH and liver fibrosis." (PMID 25502575, 2014). "Whatever the case, nardilysin seemed to play an important role in the development of steatohepatitis and liver fibrosis presumably through TNF-α activation." (PMID 24849253, 2014). "Several reports from liver fibrosis, pulmonary fibrosis and systemic sclerosis suggest an anti-fibrotic effect of anti-TNF treatment." (PMID 24678903, 2014). "Studies in vitro and in experimental models in vivo have demonstrated that TNF-α plays a role in granuloma formation and hepatic fibrosis." (PMID 24941000, 2014).
liver fibrosis (continued). "Ginsenoside Rg1, the primary active ingredient in Panax ginseng (also termed Asian or Korean ginseng), has been reported to inhibit TNF-α production and has been shown to significantly attenuate liver fibrosis development." (PMID 25431611, 2014). "Thalidomide is an effective bidirectional immunomodulatory agent that is able to suppress the generation of tumor necrosis factor-α (TNF-α) and inhibit collagen synthesis, in addition to having inhibitory effects on liver fibrosis and cirrhosis." (PMID 24520265, 2014). "TNF-α−/− mice showed reduced fibrosis after CBDL+CDL, without reduction of liver injury and inflammatory cell infiltration or enhancement of liver regeneration, indicating a direct contribution by TNF-α to liver fibrosis in CBDL+CDL mice." (PMID 23755201, 2013). "To elucidate the mechanisms by which TNF-α contributes to BDL-mediated liver fibrosis, we focused on TIMP-1, which is an endogenous inhibitor of MMPs." (PMID 23755201, 2013). "Since elevated TNF-α and IL-6 are also acknowledged to play crucial roles on hepatic fibrosis, these findings did provide a rational connection between B19 NS1 and liver fibrosis in SLE." (PMID 23840852, 2013). "Adiponectin exerts its anti-inflammatory property through suppressing TNF-α production and secretion, and alleviates hepatic fibrosis by maintaining quiescence of HSCs and inducting apoptosis of activated HSCs." (PMID 23388073, 2013). "Profibrotic factors such as IL-1α and IL-1β that play a role in liver fibrosis development, and TNF-α which is an essential cofactor of IL-13 to induce the expression of IL-13Rα2, were upregulated." (PMID 24143891, 2013). "In LPS challenge and liver fibrosis models, the proinflammatory cytokines MCP-1, KC, and RANTES were normally induced and able to compensate for loss of TNF-α and IL-6 and elicit a normal inflammatory response." (PMID 22996371, 2013). "The results, which indicate that TNF-α increases liver fibrosis through TIMP-1 production from HSCs, suggest novel therapeutic possibilities for treating liver fibrosis." (PMID 23755201, 2013). "Tissue inhibitor of metalloproteinase (TIMP)-1, the most important endogenous inhibitor of most MMPs, plays a crucial role in the pathogenesis of liver fibrosis, and its expression in HSCs is enhanced by TNF-α." (PMID 23755201, 2013). "In conclusion, we observed that TNF-α produced by cholestasis promoted liver fibrosis via TIMP-1 production from HSCs." (PMID 23755201, 2013). "Maintaining the balance of hepatic DC subsets is essential, as exemplified by chronic inflammation and the resulting hepatic fibrosis due to cDC-derived TNFα expression." (PMID 22428016, 2012). "TNF-α mRNA expression was increased after GdCl3 treatment in the lungs of rats with DMN-induced liver fibrosis." (PMID 23237422, 2012). "Osteoclastogenic proinflammatory cytokines (interleukin 1(Il-1) and tumor necrosis factor α (TNFα)) are increased in hepatic fibrosis." (PMID 23024865, 2012). "The major pathways affected by TNF-α in myotubes were those that regulate hepatic fibrosis, LXR/RXR activity, oxidative stress, mitochondrial dysfunction, and TGF-β and NF-κB signaling." (PMID 20967264, 2010). "Bioinformatics analyses of microarray dataset revealed that TNF-α affects the activity of several important pathways including those involved in oxidative stress, hepatic fibrosis, mitochondrial dysfunction, cholesterol biosynthesis, and TGF-β signaling." (PMID 20967264, 2010). "Additionally, FXR modulates inflammation by suppressing pro-inflammatory cytokines (TNF-α, IL-6) and inhibits hepatic stellate cell activation to exert anti-fibrotic effects, slowing liver fibrosis progression." (PMID 41530783, 2026). "The study’s findings suggest that the selected herbal compounds, particularly those targeting TGF-β and TNF-α, could be broadly applicable in treating liver fibrosis across different etiologies of chronic liver disease." (PMID 40575377, 2025).
liver fibrosis (continued). "Finally, inflammatory plasma cytokine levels, namely of IFN‐γ, CXCL10, and TNF, were increased in CCl4‐treated mice at peak liver fibrosis, compared with oil controls." (PMID 40760842, 2025). "Furthermore, the injection of SVF via the portal vein significantly reduced thioacetamide-induced liver fibrosis, with lower mRNA levels of IL-1β, IL-6, and TNF-α compared to the ASC and PBS-injected groups." (PMID 40547297, 2025). "D-Glucuronolactone, naturally abundant in animal livers, demonstrates hepatoprotective effects by enhancing the activity of antioxidant enzymes (SOD, GPx and GSH) and decreasing the production of inflammatory cytokines (IL-1β, IL-6 and TNF-α) in thioacetamide-induced liver fibrosis models." (PMID 41195363, 2025). "Similarly, previous study showed that ertugliflozin treated groups at different concentrations significantly lowers IL-6 and TNF-a in liver fibrosis model." (PMID 41341617, 2025). "Recent studies on the pathogenesis of liver fibrosis have indicated that the increased secretion of IL-1α/β or TNF-α by macrophages in liver fibrosis mouse models using gene knockout technology enhanced the expression of pro-fibrotic genes in HSCs, thereby exacerbating liver fibrosis." (PMID 41296792, 2025). "Studies suggest a correlation between hepatic fibrosis and TNF-α levels in patients with NASH." (PMID 41347218, 2025). "Thus, targeting TGF-β and TNF-α presents a potential therapeutic approach for treating liver fibrosis." (PMID 40575377, 2025). "This review highlights a significant increase in infiltrating monocytes in diabetic livers, with hepatic macrophages shifting to a pro-inflammatory state, elevating IFN-γ, TNF-α, IL-1β, IL-15, and IL-18, promoting inflammation, and contributing to liver fibrosis." (PMID 40362271, 2025). "Chronic increases in TNF-α also contribute to the development of liver fibrosis." (PMID 39996800, 2025). "Therefore, drugs acting by inhibiting either TGF-β or TNF-α or both can serve as a potential treatment option for treating liver fibrosis." (PMID 40575377, 2025). "According to reports, TLR4 can promote the production of inflammatory factors (such as TNF-α and IL-1β) and affect the activation of hepatic stellate cells, thus exacerbating liver fibrosis and inflammatory reactions in alcohol-induced liver injury by activating Kupffer cells." (PMID 39861457, 2025). "This analysis showed that CD11cloMinclelo macrophages produced much less TNFα than CD11chiMinclehi macrophages, and this may explain why liver fibrosis was alleviated in Lyz2Cre/+." (PMID 38831027, 2024). "TNF-α promotes TGFβ1-induced HSC activation to affect the progression of liver fibrosis." (PMID 39407108, 2024). "Pentoxifylline attenuates the development of hepatic fibrosis by inhibiting TNF-α, which reduces mortality in AH and may decrease the incidence of hepatorenal syndrome." (PMID 38650630, 2024). "Additionally, inhibiting the Notch signaling pathway to reduce TNF-α secretion by M1 macrophages can alleviate liver fibrosis." (PMID 39717848, 2024). "Suppressing M1 macrophages decreases TNF-α levels, thereby mitigating liver fibrosis." (PMID 39717848, 2024). "Its beneficial effect on hepatic fibrosis may be due to its inhibition of pro-inflammatory cytokines such as IL-6 and TNF-α in the liver; however, the other mechanisms involved in reducing hepatic fibrosis by EMPA remain unclear." (PMID 37962587, 2024). "Among the included research literatsure on TNF-α, only one was a hepatic fibrosis rats model." (PMID 38781262, 2024). "Given that COL4A1 and COL4A2 were among the most upregulated collagens in human cirrhotic livers, we hypothesized that COL4 is regulated by TNF-α and has a role in liver fibrosis and PHTN." (PMID 38713515, 2024).
liver fibrosis (continued). "For example, miR-20a-5p was downregulated during liver fibrosis and transfection of miR-20a-5p reduced the production of the proinflammatory cytokines IL-6, TNF-α, IL-18, and IFN-γ in a murine hepatoma cell line by targeting transforming growth factor beta 2 (TGFB2)." (PMID 36634655, 2023). "Moreover, MAMPs and bile acids from the intestine in PBC can promote Kupffer cells to exhibit the M1 phenotype, secrete IL-6, TNF, and IL-1β, and aggravate liver injury and liver fibrosis." (PMID 36969233, 2023). "This shows that TRAF2 also may accelerate the development of HBV-related liver fibrosis by releasing the inflammatory factors TNFα and IL8 through the TAK1/P38 or TAK1/NF-kB signaling pathways." (PMID 37091870, 2023). "TNFα levels were also significantly associated with both NASH and liver fibrosis." (PMID 36768637, 2023). "The pathogenesis of liver fibrosis is significantly impacted by TNF, IL-1 and IL-6." (PMID 37111092, 2023). "Also, another study stated that pazopanib can halt rat liver fibrosis through modulating the pro-inflammatory cytokines TNF-α and IL-6." (PMID 37458952, 2023). "Lack of improvement of liver fibrosis was associated with lower baseline values of platelet count for genotypes TNF-α-308 G/A_GG and haplotype TT/GG of IL-10-1082 T/C and IL-10-592 G/T." (PMID 36674897, 2023). "Furthermore, the liver fibrosis group had significantly higher TNFα and IL8 mRNA levels than the control group." (PMID 37091870, 2023). "A quantitative analysis showed that the inflammatory infiltration area increased significantly in the livers of 4.5-month-old TNF-Tg mice compared to that in WT mice, and the area of liver fibrosis was significantly increased in 4.5- and 5.5-month-old TNF-Tg mice." (PMID 37784156, 2023). "In addition, hepatic NKp44+NK cells from patients with HCV infection were positively correlated with liver fibrosis and viral load, producing TNF-α to promote liver injury." (PMID 37239062, 2023). "Mechanistically, we showed that accumulation of liver fibrosis-related cytokines, including TGFβ, IFNγ, TNFα, etc, could induce UC-MSC senescence and SASP through activation of JAK/STAT3 signaling pathway." (PMID 37507381, 2023). "We analyzed the protein expression of TNF-α and NF-κB to determine whether Brg1 hepatocyte deletion impacts the TNF-α/NF-κB pathway in CCl4-induced liver fibrosis." (PMID 38033027, 2023). "The improvement of liver fibrosis after treatment was associated with the presence of allele A of TNF-α-308 G/A and non-improvement with haplotype TT/GG of IL-10-592 G/T and IL-10-1082 T/C." (PMID 36674897, 2023). "According to this study, DPx potently inhibited pro-inflammatory cytokines (IL-1, IL-6, and TNF-α), which may be key factors in preventing hepatic fibrosis." (PMID 37324954, 2023). "In addition, NASH patients were shown to overexpress TNFα in both liver and adipose tissue, and enhanced expression of both TNFα and TNFR1 were associated with advanced liver fibrosis." (PMID 36768637, 2023). "TNF-α can also promote the recruitment of proinflammatory neutrophils and macrophages and the activation of fibrogenic pathways leading to the development of liver fibrosis." (PMID 37762434, 2023). "Moreover, a significant positive correlation was found between the relative abundances of Streptococcus and Ruminococcus and TNF-α in the BSA-induced liver fibrosis rats." (PMID 37781475, 2023). "In bile duct ligation (BDL) mice, toxic bile acids further activate NLRP3 inflammasome assembly and cause Kupffer cells to develop the M1 phenotype, leading to the production of proinflammatory cytokines, including IL-6, TNF, and IL-1β, which aggravate liver fibrosis and damage." (PMID 36969233, 2023). "TNF, IL-1β, and IL-6 have a significant impact on the etiology of liver fibrosis." (PMID 36703748, 2022).
liver fibrosis (continued). "DNTs in normal subjects also express high levels of TNF-α, but the expression levels of DNTs TNF-α in liver fibrosis are even higher, indicating that DNTs in liver fibrosis may exert their effect via TNF-α." (PMID 35371052, 2022). "In addition, previous studies demonstrated an inflammation-associated correlation between TNF-α and α-SMA, a marker of myofibroblast development, and PL decreased the expression of α-SMA and TNF-α and improved liver fibrosis." (PMID 36271442, 2022). "Patients with hepatic steatosis may proceed to hepatic fibrosis because of increased production of the proinflammatory cytokine tumor necrosis factor-alpha in the Kupffer cells, which enhances oxidative stress." (PMID 36466832, 2022). "Furthermore, the pharmacological effects of P. chinense on these proteins were verified by CCl4-induced rat liver fibrosis, and P. chinense was found to improve liver functions through regulating TNF-α, Timp1, and HO-1 expressions." (PMID 35721129, 2022). "Interestingly, interferon gamma (IFN-γ) increased but TNF-α, interleukin 6 (IL-6), hepatic fibrosis, and steatosis decreased in the add-on groups." (PMID 35889747, 2022). "Moreover, TNF-α, along with TGFβ, are key pro-inflammatory cytokines involved in the development of liver fibrosis." (PMID 36005132, 2022). "TNF is largely a set of pro-inflammatory cytokines recognized to play an essential part in inducing liver fibrosis, and there is evidence that oxidative stress and endotoxins may work together to promote TNF production." (PMID 36703748, 2022). "Additionally, the upregulation of TNF-α in the group of people who had consumed Fe2O3-NPs suggested that it had a significant role in liver fibrosis and inflammation by activating NF-KB, which is an inflammatory trigger." (PMID 36080111, 2022). "GXZY might affect the MAPK signaling pathway, TNF signaling pathway, hepatitis B, and pathways in cancer and prevent the progress of liver fibrosis and the occurrence of liver cancer." (PMID 35330838, 2022). "Liver injury may retain the active surface of HSCs and accelerate the migration of inflammatory cells to the injured liver, secreting a significant number of inflammatory mediators such as TNF-α, IL-6, and IL-1β to enhance the development of liver fibrosis." (PMID 36017390, 2022). "Tim-3 may promote the progression of liver fibrosis by regulating the secretion of cytokines (TNF-α, IL-10, and IFN-γ) by immune cells, thereby regulating the progression of liver disease." (PMID 35646962, 2022). "In addition, western blot analysis showed that the M2 macrophage markers, CD206 and CD163, were upregulated at the 8th week, whereas the M1 macrophage marker, TNFα, was upregulated at the 16th week of the β1-AA-induced hepatic fibrosis." (PMID 35983976, 2022). "TNF signaling appears to be crucial in triggering liver inflammation, neutrophils and pro-inflammatory macrophage recruitment, as well as in activation of fibrogenic pathways that are central to the development of liver fibrosis." (PMID 35002463, 2022). "TNF-α stimulation can activate LX-2 cells to construct a cell model of liver fibrosis." (PMID 35043727, 2022). "Another important miRNA is miR-155, a major regulator of increased Kupffer cell activation and TNF-α production, and is also involved in ethanol-induced liver fibrosis and steatohepatitis by mediating the peroxisome proliferator-activated receptor response element (PPRE) and PPARα pathway." (PMID 34068269, 2021). "This study demonstrated that TNFα mediates liver fibrosis-induced muscle atrophy." (PMID 33414474, 2021). "Therefore, inhibiting TNFα signalling in the skeletal muscles where TNFα functions as an atrophy-inducing factor can be an effective preventive strategy for liver fibrosis-induced muscle atrophy." (PMID 33414474, 2021).